CES4A (carboxylesterase 4A)
Description:
Probable carboxylesterase.
Synonyms: CES8; FLJ37464; CES6
Tractability: Small molecule: it belongs to a druggable protein family. Antibody: UniProt places it where antibodies can reach, with high confidence; UniProt predicts a signal peptide or a membrane-spanning region; its Gene Ontology location is reachable by antibodies, with medium confidence.
Gene: Protein-coding gene on chromosome 16 (66,988,585 to 67,010,417, forward strand). Ensembl gene ENSG00000172824.
Subcellular location: Secreted
Subcellular location (Human Protein Atlas): Cytosol; Predicted to be secreted
Gene Ontology:
Molecular function: carboxylesterase activity
Cellular component: extracellular region
Genetic constraint (gnomAD): Loss-of-function variants: 49 observed, 65.26 expected, observed/expected ratio (o/e) 0.75, 90% interval 0.6 to 0.95. The upper end of that interval is the gene's LOEUF score, 0.95, which puts it in group 4 of 6, group 1 being the genes least tolerant of losing a copy. Missense variants: 685 observed, 729.77 expected, observed/expected ratio (o/e) 0.94, 90% interval 0.88 to 1. Synonymous variants: 247 observed, 283.39 expected, observed/expected ratio (o/e) 0.87, 90% interval 0.79 to 0.97.
Homologues: Orthologues: rabbit CES4A (75% identical), mouse Ces4a (71% identical), rat Ces4a (70% identical), guinea pig CES4A (56% identical), zebrafish ces3 (36% identical), zebrafish nlgn2b (35% identical), zebrafish ces2a (35% identical), zebrafish nlgn3b (33% identical), Drosophila melanogaster Jhe (30% identical), Drosophila melanogaster gas (29% identical), Caenorhabditis elegans ace-4 (29% identical), Caenorhabditis elegans ace-3 (28% identical), and 40 more. Paralogues in human: CES1 (43% identical), CES5A (42% identical), CES2 (41% identical), CES3 (41% identical), ACHE (34% identical), NLGN4Y (34% identical), NLGN2 (34% identical), NLGN3 (34% identical), NLGN4X (34% identical), NLGN1 (33% identical), BCHE (30% identical), TG (29% identical), and 1 more.
Diseases named in the same sentence as CES4A in open-access papers:
CES4A is named in the same sentence as 2 diseases in open-access papers, as found by Europe PMC text mining. Sharing a sentence is not in itself a finding about the gene and the disease. The quoted sentences say what the papers report.
cancer (2 papers, 2023 to 2025). A tumor composed of atypical neoplastic, often pleomorphic cells that invade other tissues. "For the remaining genes, OR10A3, RPF1, KΑTNA1, and CES4A, in our risk score model, no specific relationship to cancer had been reported yet, further exploration should be carried out for their roles in the prognosis in DLBCL patients." (PMID 36816541, 2023).
CES4A also shares sentences with these, for which no sentence is quoted: angiosarcoma (1 paper).